TRPM8 (transient receptor potential cation channel subfamily M member 8)
Diseases named in the same sentence as TRPM8 in open-access papers (continued):
Sharing a sentence is not in itself a finding about the gene and the disease.
liver fibrosis (4 papers, 2022 to 2025). "Further, transcriptomic analyses of mRNAs using fibrotic mice liver specimens, coupled with both in vitro and in vivo assays, were conducted to understand the underlying molecular mechanism of TRPM8 in liver fibrosis." (PMID 35525986, 2022). "A strong correlation between TRPM8 deficiency and alleviated liver fibrosis progression was also observed in CCl4- and BDL-treated mice." (PMID 35525986, 2022). "Taken together, these results imply TRPM8 deficiency may attenuate liver fibrosis by downregulating the expression of the pro-inflammatory factor S100A9 while promoting the expression of HNF4α." (PMID 35525986, 2022). "In conclusion, our results suggest that TRPM8 inhibition may alleviate the liver fibrosis caused by inflammation and cholangiopathies through S100A9-HNF4α signaling." (PMID 35525986, 2022). "To conclude, the upregulation of TRPM7, TRPM8, TRPV3, TRPV4, and TRPC6 is significantly associated with the onset and progression of liver fibrosis." (PMID 37569884, 2023). "The inhibition of TRPM8 has the potential to mitigate liver fibrosis by downregulating the expression of the pro-inflammatory factor S100A9 and promoting the expression of HNF4α." (PMID 37569884, 2023). "The present study showed that TRPM8 is upregulated in both human liver fibrosis tissues and specimens collected from two murine fibrosis models, namely the CCl4-induced and BDL-treated mice." (PMID 35525986, 2022). "TRPM8 deficiency seemed to significantly attenuate the progression of liver fibrosis in fibrotic mice; thus, we next investigated the potential therapeutic effect of TRPM8 specific inhibitor (M8-B hydrochloride) and agonist (WS-12) on liver fibrosis." (PMID 35525986, 2022). "The effect of TRPM8 was evaluated using specimens obtained from classic murine models of liver fibrosis, namely wild-type (WT) and TRPM8−/− (KO) fibrotic mice after carbon tetrachloride (CCl4) or bile duct ligation (BDL) treatment." (PMID 35525986, 2022). "Their investigation revealed a notable increase in TRPM8 expression within liver fibrosis tissue." (PMID 37569884, 2023). "Here, we report the functional significance of TRPM8 in liver fibrosis." (PMID 35525986, 2022). "Furthermore, RNA sequencing and morphological examination were conducted to reveal the molecular mechanism of TRPM8 in the pathogenesis of liver fibrosis." (PMID 35525986, 2022). "In summary, these results strongly suggest inhibiting TRPM8 may be a promising therapeutic approach for treating liver fibrosis." (PMID 35525986, 2022). "Herein, we assessed the potential effect of TRPM8 in liver fibrosis." (PMID 35525986, 2022). "Notably, the obtained data suggest genetic inactivation of TRPM8 is able to intervene and effectively attenuate the progression of liver fibrosis in mice." (PMID 35525986, 2022). "TRPM8 may be a potential therapeutic target for liver fibrosis." (PMID 35525986, 2022). "In accordance with these findings, our data show that inhibition of TRPM8 upregulated the expression of HNF4α in both CCl4- and BDL-treated models, suggesting its involvement in the process of liver fibrosis." (PMID 35525986, 2022). "In this study, we found that TRPM8 inhibition could reduce the F4/80 positive cell population and inhibit the transcript levels of IL-6, IL-1β, TNFα, and MCP-1 in murine models of liver fibrosis." (PMID 35525986, 2022). "Moreover, the inhibition of TRPM8 has been observed to decrease the number of F4/80-positive cells and suppress the activation of HSCs and cholangiocytes by reducing gene expression levels of IL-6, IL-1β, TNFα, and MCP-1 in a mouse liver fibrosis model." (PMID 37569884, 2023).
squamous cell carcinoma (4 papers, 2021 to 2025). A carcinoma arising from squamous epithelial cells. "Migration and invasion of squamous carcinoma cell is more in case of TRPM8 activation and less in case of inhibition." (PMID 39150496, 2024).
cervical cancer (3 papers, 2022 to 2023). A primary or metastatic malignant neoplasm involving the cervix. "Since these results have also been validated in breast and cervical cancer cells, the TRPM8-Rap1 interaction could constitute a therapeutic target against metastatic progression in several types of tumors." (PMID 35565390, 2022). "Moreover, in this study, we demonstrated that the binding of TRPM8 with Rap1, mainly supported by E207 and Y240 residues in its N-terminal tail, affects cell adhesion not only in metastatic PCa cells but also in other cancer models like breast and cervical cancer, though to a different extent." (PMID 35565390, 2022).
diabetes (3 papers, 2007 to 2026). "Given that TRPM8 and the PKA/CREB pathway have been found to be associated with diabetes and AML, respectively, the expression of TRPM8, CREB, and PKA in PFC was investigated in an acute seizure mouse model." (PMID 41474182, 2026). "GCA bound to TRPM8, inactivated the ERK/HIF‐1/VEGF pathway, and impaired angiogenesis in diabetes." (PMID 38308197, 2024).
fatty liver disease (3 papers, 2018 to 2025). A reversible condition wherein large vacuoles of triglyceride fat accumulate in liver cells via the process of steatosis. "The gross morphology showed that livers of WT mice became slightly pale at 24 h after PH, but livers of TRPM8 KO mice were obviously pale, indicating that hepatic steatosis may be more serious compared to WT mice." (PMID 36526620, 2022).
heartburn (3 papers, 2022 to 2024). "A recent in vivo study in humans demonstrated how oesophageal infusion of TRPM8 agonist menthol induced heartburn in GORD patients, while the infusion of cold water induced oesophageal pain." (PMID 36768825, 2023). "Collectively, these studies suggest a distinctive nociceptive role for TRPM8 in heartburn pathogenesis." (PMID 36768825, 2023). "This possibility is further supported by the ability of menthol (TRPM8 agonist) infusion to elicit cold sensations in the esophagi of healthy subjects compared to the heartburn evoked in GERD patients." (PMID 35562940, 2022). "Further inquiry into the molecular underpinnings of esophageal spasm may yield insights for treating spasm-related pain and gastroesophageal reflux disease through TRPM8 modulation." (PMID 39062591, 2024). "Building on the findings regarding the inhibitory impact of TRPM8 on TRPV1 in analogous research, it is anticipated that TRPM8 may emerge as a promising target for reflux esophagitis treatment." (PMID 39062591, 2024).
ischemic stroke (3 papers, 2022 to 2025). A stroke disorder caused by obstruction of blood flow to the brain, due to thrombotic (local blood clot formation) or embolic (due to a blood clot or other material traveling from another site) event. "Menthol improves the outcome of ischemic stroke in mice by targeted activation of TRPM8, and these effects are currently being investigated in a clinical trial (NCT05877079)." (PMID 41399206, 2025). "These beneficial effects can be reversed by the TRPM8 antagonist AMTB or lidocaine, or by Trpm8 knockout, highlighting TRPM8's therapeutic potential in ischemic stroke treatment." (PMID 41399206, 2025). "Beyond pain, some findings suggest potential applications for TRPM8 activation in other conditions, such as ischemic stroke, where peripheral TRPM8 activation has demonstrated neuroprotective effects." (PMID 39684707, 2024). "Our results show that topically applied menthol to mouse paws reduced oxidative stress and neuroinflammation and thus improved ischemic stroke via activation of the peripheral ion channel TRPM8." (PMID 35897101, 2022). "The TRPM8 channel contributes to the cooling sensation of menthol, and cooling body temperature demonstrated therapeutic effectiveness after ischemic stroke." (PMID 35897101, 2022). "We used Trpm8 gene knockout (Trpm8−/−) mice or TRPM8 antagonist and lidocaine to validate the roles of TRPM8 and peripheral nerve conduction in menthol against ischemic stroke." (PMID 35897101, 2022). "TRPM2, TRPV2, and TRPV4 exacerbate ischemic stroke, while TRPM8 plays a protective role." (PMID 41399206, 2025). "In contrast, TRPM8 activation shows neuroprotection in ischemic stroke." (PMID 41399206, 2025). "In the present study, we identified whether activating peripheral TRPM8 can be an adjuvant therapy for ischemic stroke." (PMID 35897101, 2022).
neuroblastoma (3 papers, 2014 to 2023). Neuroblastoma (NB) is the most common solid, extracranial childhood tumor. "This is the first study to report expression of modified human TRPM8 or TRPA1 proteins in human SH-SY5Y neuroblastoma cells and we present several significant findings." (PMID 24975826, 2014). "Therefore DNA expression constructs containing human TRPM8 or TRPA1 cDNAs were transfected into HEK (human embryonic kidney cells)-293 or SH-SY5Y neuroblastoma cells and G418 resistant clones analysed for effects of agonists and antagonists on intracellular Ca2+ levels." (PMID 24975826, 2014). "In this study, we used site-directed mutagenesis, recombinant DNA engineering and measurements of agonist-induced Ca2+ influx to characterize TRPM8 and TRPA1 channel function in neuroblastoma cell culture." (PMID 24975826, 2014). "In this respect, SH-SY5Y cells, a human neuroblastoma line capable of neurotransmitter biosynthesis and in vitro neuronal dendrite extension, were recently stably transfected with TRPV1, but studies with TRPM8 and TRPA1 have not been reported previously." (PMID 24975826, 2014).
neuroendocrine tumor (3 papers, 2018 to 2024). "Notably, an increase in TRPM8 expression was observed in neuroendocrine tumor cells, and this rise was associated with an increased release of neurotensin." (PMID 38339011, 2024). "For example, TRPM8 channels regulate neurotensin secretion in neuroendocrine tumor cells)." (PMID 38339011, 2024).
oropharyngeal dysphagia (3 papers, 2018 to 2023). "In conclusion, our systematic review found that TRPV1, TRPA1 and TRPM8 agonists have beneficial effects for patients with neurogenic oropharyngeal dysphagia when compared to placebo interventions." (PMID 34337829, 2022). "Furthermore, in clinical studies, TRPV1, TRPA1, and TRPM8 agonists improved the efficacy, safety, and physiology of swallowing in patients with oropharyngeal dysphagia." (PMID 36909278, 2023). "In another study in oropharyngeal dysphagia patients, a TRPV1 agonist (capsaicinoid, 150 μM) had a better therapeutic effect on improving swallowing compared with a TRPM8 agonist (menthol, 1 mM or 10 mM)." (PMID 30567389, 2018).
overactive bladder (3 papers, 2010 to 2024). Symptom of overactive detrusor muscle of the urinary bladder that contracts with abnormally high frequency and urgency. "For instance, an overactive bladder aggravated by cold temperatures results from increased expression of TRPM8 channels on bladder afferent nerve fibers, highlighting the essential role of TRPM8 in the lower urinary tract." (PMID 37388453, 2023). "Through antagonistic assays, the researchers illustrated the TRPM8 inhibitory effects of flavone aglycones found in traditional herbal extracts, suggesting potential clinical relevance due to the known benefits of TRPM8 inhibitors in treating symptoms of overactive bladder." (PMID 39114124, 2024).
Parkinson disease (3 papers, 2023 to 2024). A progressive degenerative disorder of the central nervous system characterized by loss of dopamine producing neurons in the substantia nigra and the presence of Lewy bodies in the substantia nigra and locus coeruleus. "Notably, the patients of Parkinson's disease experience a chronic pain which is found to be associated with TRPM8 gene." (PMID 39150496, 2024). "TRPM8 is also considered a risk factor in the case of Parkinson's disease." (PMID 39150496, 2024). "Additionally, the expression of TRPM8 gene has been reported to be upregulated in the presence of MPP (Methyl-4-phenylpyridinium), a metabolite used to induce Parkinson's disease in neuronal cell lines (Öz and Çelik 2022)." (PMID 39150496, 2024).
prostate metastatic cancer (3 papers, 2016 to 2021). "The hormone sensitive lymph node derived metastatic prostate cancer cell line LNCaPFGC were choose as the best proxy to study the possible impact of TRPM8 agonists on either enzalutamide or docetaxel efficacy." (PMID 34514058, 2021). "Since migration is one of the key processes of metastatic development, these results suggest a protective role for TRPM8 in prostate metastatic cancer progression." (PMID 27409624, 2016). "Highly expressed in the prostate epithelium within the human body, Transient Receptor Potential subfamily M member 8 (TRPM8) levels rise in primary and hormone naïve metastatic prostate cancer (PCa) lesions, which makes this channel an interesting prototype of molecular target." (PMID 34514058, 2021). "Because migration is a key process during metastatic development, these results strengthen the hypothesis that TRPM8 exerts a protective role against prostate metastatic cancer progression." (PMID 31138874, 2019). "Furthermore, our results demonstrate that LNC600-WS12 can be used to target the TRPM8 channel and that encapsulation potentiated its protective role against prostate metastatic cancer progression." (PMID 31138874, 2019).
allergic disease (2 papers, 2024 to 2025). An immune response that occurs following re-exposure to an innocuous antigen, and that requires the presence of existing antibodies against that antigen. "In animal models of post-inflammatory colonic allergy, elevated TRPM8 expression markedly reduced hypersensitivity to mechanical stimulation and alleviated allergy symptoms." (PMID 40053041, 2025). "In conclusion, TRPM8 plays a significant role in neuroimmunity in allergic diseases, but further exploration is needed to understand the involvement of nociceptive neuronal TRPM8 in AR." (PMID 39185421, 2024).
Anxiety (2 papers, 2019 to 2023). Intense feelings of nervousness, tension, or panic often arise in response to interpersonal stresses. "TRPM8 rs7577262 was associated with anxiety (ORadj = 0.27, 95% CI = 0.10–0.76, p = 0.011)." (PMID 37303955, 2023). "The TRPM8 rs10166942 T allele was still independently associated with chronic migraine (adjusted odds ratio = 1.62, p = 0.004) after controlling for age, gender, education, body mass index, depression and anxiety using a multivariable logistic regression in both discovery and replication cohorts." (PMID 31842742, 2019).
Arthritis (2 papers, 2018 to 2023). Inflammation of a joint. "Because hyperplasia and secretion of pro-inflammatory compounds are two known roles of synoviocytes in arthritis, further investigation of intra-articular application of menthol or other TRPM8 agonists may reveal a mechanism leading to reduced pathology of joint tissues under arthritic conditions." (PMID 30326593, 2018). "In summary, the current data suggests that agonism of TRPC5, TRPM3, TRPM8, and TRPV2 may help ameliorate or prevent arthritis, while antagonism of TRPM7 and TRPV4 may have a similar effect." (PMID 30326593, 2018).
bladder disorders (2 papers, 2006 to 2019). "For example, Kissei Pharmaceutical Co. described novel α-arylglycinamides, as the TRPM8 antagonists, playing important roles in bladder diseases." (PMID 31141957, 2019).
breast adenocarcinoma (2 papers, 2010 to 2022). "In ER+ grade I breast adenocarcinomas, TRPM8 expression is normally upregulated, with comparatively higher expression of TRPM8 mRNA in the highly invasive MDA-MB-231 cell line." (PMID 36844925, 2022). "Our results show, for the first time, that TRPM8 protein is over-expressed in human breast adenocarcinomas and that this over-expression is specifically correlated with ERα expression." (PMID 20482834, 2010). "Immuno-histochemical examination of the expression of TRPM8 channels in human breast tissues revealed an over-expression of TRPM8 in breast adenocarcinomas, which is correlated with estrogen receptor positive (ER+) status of the tumours." (PMID 20482834, 2010).
depression (2 papers, 2019 to 2023). "TRPM8-rs10166942 was associated with depression risk in recessive model (ORadj = 0.51, 95% CI = 0.27–0.94, p = 0.034) and additive model (ORadj = 1.98, 95% CI = 1.06–3.77, p = 0.034)." (PMID 37303955, 2023). "SLC17A8 rs11110359, TRPV4 rs3742037 and TRPM8 rs17862920 were associated with depression in dominant model (ORadj = 0.42, 95% CI = 0.20–0.84, p = 0.016; ORadj = 2.03, 95% CI = 1.06–3.96, p = 0.035; ORadj = 0.48, 95% CI = 0.23–0.96, p = 0.042, respectively)." (PMID 37303955, 2023). "TRPV4 rs3742037, TRPM8 rs17862920 and SLC17A8 rs11110359 were associated with depression in dominant model [ORadj (95% CI): 2.03 (1.06–3.96), p = 0.035; 0.48 (0.23–0.96), p = 0.042; 0.42 (0.20–0.84), p = 0.016, respectively]." (PMID 37303955, 2023).
diabetic neuropathy (2 papers, 2007 to 2025). A chronic, pathological complication associated with diabetes mellitus, where nerve damages are incurred due to diabetic microvascular injury involving small blood vessels that supply these nerves, resulting in peripheral and/or autonomic nerve dysfunction. "Collectively, this research delineates that Aju-I mitigates pain behaviors in the streptozotocin (STZ)-induced diabetic neuropathy model by modulating the Nrf2/Keap-1/HO-1 signaling pathway and the activity of TRPV1/TRPM8 nociceptors." (PMID 40264787, 2025).
ductal adenocarcinomas (2 papers, 2010 to 2023). "Statistical analysis revealed that the over-expression of TRPM8 in tumoral tissues was observed in 65.4% of the 26 ductal adenocarcinomas tested." (PMID 20482834, 2010).
Dysphagia (2 papers, 2018 to 2020). "In addition, in aged people with dysphagia, a TRPV1 or TRPM8 agonist (capsaicin or menthol) applied to the pharynx significantly shortened the latency of the evoked swallowing reflex compared with that for distilled water." (PMID 30567389, 2018).
epileptic seizures (2 papers, 2021 to 2026). "To elucidate the effects of TRPM8 channel absence on the development of EDs and epileptic seizures, we compared EDs and seizure scores between WT and TRPM8KO mice." (PMID 34658898, 2021). "We investigated the effects of TRPM8 agonist and lack of TRPM8 channels on EDs and epileptic seizures." (PMID 34658898, 2021). "This study investigated changes in EDs and epileptic seizures in a model lacking TRPM8 channels, as well as the effects of TRPM8 agonist on EDs and epileptic seizures." (PMID 34658898, 2021). "However, the effects of no TRPM8 channels on EDs and epileptic seizures is unclear." (PMID 34658898, 2021).
Fever (2 papers, 2020 to 2021). Body temperature elevated above the normal range. "The present study showed that the i.c.v. injection of PGE2 generated fever in TRPM8 KO mice in a similar manner to WT mice, indicating that TRPM8 KO mice preserve the ability generating fever." (PMID 34589786, 2021). "Moreover, a study to explore the possible mechanism of Dahuang’s antipyretic effect on yeast-induced pyrexia rats found that Dahuang reduced rectal temperature; importantly, it inhibited the fever-induced expression of TRPV1 and enhanced TRPM8 in hypothalamus and DRG." (PMID 33542688, 2020).